FGFR3 (fibroblast growth factor receptor 3)
Diseases named in the same sentence as FGFR3 in open-access papers (continued):
Sharing a sentence is not in itself a finding about the gene and the disease.
thanatophoric dysplasia (continued). "Thanatophoric dysplasia (TD) is the most common lethal skeletal dysplasia, caused by de novo fibroblast growth factor receptor 3 (FGFR3) mutations." (PMID 42083712, 2026). "Thanatophoric dysplasia (TD) is a severe skeletal dysplasia caused by heterozygous mutations in the gene encoding fibroblast growth factor receptor 3 (FGFR3)." (PMID 34597445, 2021). "Thanatophoric dysplasia (TD) is a severe genetic skeletal dysplasia that results from missense mutations in FGFR3 (fibroblast growth factor receptor 3), which cause a constitutive activity of the receptor." (PMID 33996819, 2021). "Gain-of-function mutation of FGFR3 promotes chondrocyte apoptosis in thanatophoric dysplasia (TD) mice." (PMID 27041213, 2016). "The corresponding kinase-domain mutations in human FGFR3 are known to cause a severe and fatal form of achondroplasia, known as thanatophoric dysplasia (TD; OMIM#187601)." (PMID 19192266, 2009). "Other genomic diagnoses not included in the clinical outcome audit, include DNAL1 (Primary ciliary dyskinesia 16, MIM: 614017), SPAST (Spastic paraplegia 4, MIM:182601) and FGFR3 (Thanatophoric dysplasia, MIM:187600)." (PMID 38577897, 2024). "Gain-of-function FGFR3 mutations lead to dwarfism (ACH, hypochondroplasia, and thanatophoric dysplasia) but also craniofacial suture fusions (craniosynostoses: Muenke syndrome and Crouzon syndrome with acanthosis nigricans)." (PMID 37072824, 2023). "Pathogenic variants in FGFR3 are associated with several skeletal disorders, including ACH, HPP, and thanatophoric dysplasia." (PMID 37548766, 2023). "For example, identical FGFR3 mutations in mosaic form produce epidermal nevi (MIM162900), whereas in the germline, they cause thanatophoric dysplasia (MIM 187600)." (PMID 36566878, 2023). "Mutations in FGFR3 have been associated with various SDs, including ACH, HCH, thanatophoric dysplasia, Muenke syndrome, and ACH with developmental delay and acanthosis nigricans (SADDAN)." (PMID 37548766, 2023). "It is present in varying severity and varying frequency in many other FGFR3 disorders, including hypochondroplasia, thanatophoric dysplasia, SADDAN syndrome, Crouzon syndrome with acanthosis nigricans, and in isolation with little or no skeletal abnormality." (PMID 30606190, 2019). "Examples include the G370C, S371C and Y373C mutations implicated in thanatophoric dysplasia type 1 (TD1), expected to stabilize the FGFR3 dimers via disulfide bonds." (PMID 23437153, 2013). "Germinal activating FGFR3 mutations result in craniosynostoses and dwarfing chondrodysplasias of varying severity (hypochondroplasia, achondroplasia, SADDAN and thanatophoric dysplasia)." (PMID 15869706, 2005). "Thanatophoric dysplasia (TD) is the most common lethal congenital skeletal dysplasia, characterized by severe micromelia, a narrow thorax, and frontal bossing due to activating mutations in the fibroblast growth factor receptor 3 (FGFR3) gene on chromosome 4p16.3." (PMID 41869141, 2026). "No FGFR3 mutations c.742C>T, c.1118A>G, or c.1948A>G, which are linked to thanatophoric dysplasia (TD), were detected." (PMID 40149896, 2025). "Our study addresses this gap by examining the testis-expansion patterns, as well as the increases in mutations in sperm for two FGFR3 variants—c.1138G>A (p.G380R) and c.1948A>G (p.K650E)—which are associated with ACH or thanatophoric dysplasia (TDII), respectively." (PMID 38397181, 2024). "FGFR3 mutations are associated with thanatophoric dysplasia (TD), an autosomal dominant disorder, which was the initial diagnostic hypothesis (DH) for the three samples in which we detected the mutation NM_000142:c.742C > T:p.R248C, the most common mutation associated with TD type I." (PMID 30043834, 2018). "Gain-of-function mutations of FGFR3 cause several short-limbed skeletal dysplasias such as hypochondroplasia (HCH), severe ACH with developmental delay and acanthosis nigricans (SADDAN), and thanatophoric dysplasia (TD) types I and II." (PMID 24324705, 2013).
hypochondroplasia (66 papers, 2009 to 2025). "Macrocephaly at birth and PNGR raised SRS suspicion for the SRS03 girl, but the FGFR3 variant was consistent with a diagnosis of hypochondroplasia." (PMID 39412159, 2025). "Pathogenic variants in FGFR3 are known to cause autosomal dominant achondroplasia and hypochondroplasia." (PMID 37880672, 2023). "Case 19 harbored a variant c.1620C>A (p.N540K) in the TK-1 domain of FGFR3, which is a common cause of hypochondroplasia (MIM_146,000)." (PMID 36923788, 2023). "In case 1a, the paternally inherited FGFR3 c.1620C>G variant was detected by Sanger sequencing in two EVTs, indicating that the fetus was affected with hypochondroplasia." (PMID 37829280, 2023). "The proband with an FGFR3 mutation, a female 4 and 3/12 years of age, was diagnosed with hypochondroplasia." (PMID 34740356, 2021). "The diagnosis of hypochondroplasia is based on clinical manifestations, radiological features and FGFR3 mutation analysis." (PMID 34740356, 2021). "Fetus 13 inherited a heterozygous mutation c.1620C > G (p.Asn540Lys) in the TK-1 domain of FGFR3, which is a common cause of hypochondroplasia (OMIM_146000)." (PMID 34567078, 2021). "Other less frequent mutations are also identified in FGFR3 but are mainly associated with hypochondroplasia and thanatophoric dysplasia type I and II." (PMID 28679403, 2017). "At least some of these mutations are likely to have clinical relevance and they include a gatekeeper mutation (FGFR3 V555M) and a mutation (corresponding to FGFR3 I538V) also identified in a developmental disorder (hypochondroplasia)." (PMID 26992226, 2016). "By contrast, p.Lys650Asn and p.Lys650Gln mutations that activate the FGFR3 to a lesser degree are associated with milder forms of skeletal dysplasia, such as hypochondroplasia." (PMID 25505998, 2014). "We aim to describe the association of hypochondroplasia, acanthosis nigricans, and insulin resistance in a child harboring FGFR3 mutation." (PMID 25505998, 2014). "Here, we analyzed the impact of Fgfr2- and Fgfr3-activating mutations on mandibular bone formation and endochondral bone repair after non-stabilized mandibular fractures in mouse models of Crouzon syndrome (Crz) and hypochondroplasia (Hch)." (PMID 39837840, 2025). "The majority of children with hypochondroplasia harbor activating variants in the FGFR3 gene, although patients may be diagnosed on clinical and radiological grounds alone." (PMID 38813446, 2024). "Finally, temporal lobe abnormalities have also been described in cases of thanatophoric dysplasia, achondroplasia, and hypochondroplasia caused by mutations in FGFR3, as well as in Pfeiffer syndrome caused by a mutation in FGFR2." (PMID 39735065, 2024). "In addition, in patients with hypochondroplasia and Muenke's syndrome with coronal craniosynostosis, due to a mutation in the FGFR3 gene, bilateral dysgenesis of the medial temporal lobes was observed." (PMID 39735065, 2024). "The present findings emphasize the detrimental effect of gain-of-function mutations in the Fgfr3 gene on long bone modeling during both developmental and aging processes, with potential implications for the management of elderly patients with hypochondroplasia and osteoporosis." (PMID 37345656, 2023). "Heterozygous gain-of-function mutations in the FGFR3 cause achondroplasia and hypochondroplasia." (PMID 30864634, 2019). "Different mutations in FGFR3 have been identified in patients with hypochondroplasia (HCH)." (PMID 30635042, 2019). "Insulin insensitivity and acanthosis nigricans are uncommonly seen in hypochondroplasia patients with FGFR3 mutations which may represent a new association." (PMID 25505998, 2014). "Furthermore, equivalent substitutions in FGFR3 (p.(Asn540Lys), p.(Asn540Thr) and p.(Asn540Ser)) are known to result in gain of function and to cause hypochondroplasia (MIM 146000), an autosomal dominant skeletal dysplasia characterized by disproportionate short stature." (PMID 38265560, 2024).
hypochondroplasia (continued). "Hypochondroplasia (HCH) is a mild dwarfism caused by missense mutations in fibroblast growth factor receptor 3 (FGFR3), with the majority of cases resulting from a heterozygous p.Asn540Lys gain-of-function mutation." (PMID 37345656, 2023). "Taken as a whole, our findings suggest that both MAPK and STAT pathways are over-activated in the bone callus in a mouse model of hypochondroplasia, and thus highlight the key role of these downstream signaling pathway in FGFR3-related disorders." (PMID 39837840, 2025). "Although there is an evident abnormal proportion in patients with hypochondroplasia and FGFR3 alterations is rare in patients classified as ISS, some children still can be undiagnosed at first evaluation." (PMID 30864634, 2019). "For example, a patient with the dominantly inherited SNV Gly382Arg (c.1138 G > A, rs28932614) in FGFR3 had the genetic disorder, hypochondroplasia (OMIM 146000)." (PMID 28851938, 2017). "The work of Bellus compared the ligand-independent activity of FGFR3 carrying three different mutations: the K650E mutation linked to TDII, the K650M mutation causing SADDAN, and the K650N and K650Q mutations associated with hypochondroplasia." (PMID 22529939, 2012). "One FGFR3 mutation (c.1620C>A p.N540K), one likely pathogenic GNAS mutation (c.2288C>T p.A763V), and one TRPS1 mutation (c.2527_c.2528dupTA p.S843fsX72) was identified in three pedigrees with hypochondroplasia, pseudohypoparathyroidism Ia (PHP-Ia), and trichorhinophalangeal syndrome type I (TRPS I)." (PMID 34740356, 2021). "Prior to this genetic analysis, the patient and several of his living family members had been clinically diagnosed with hypochondroplasia despite no disease-causing variation in the FGFR3 gene being identified through previous genetic testing at a different laboratory." (PMID 34627339, 2021).
lung cancer (66 papers, 2013 to 2025). A malignant neoplasm involving the lung. "In previous reports, FGFR3 expression was associated with lung cancer, whereas FGFR2 played an important role in alveolar epithelial cell homeostasis and survival following injury." (PMID 38916962, 2024). "Subsequent to the first report of IGF-1R activation in 2010, AXL, Notch3, and fibroblast growth factor receptor 3 (FGFR3) are identified as receptor tyrosine kinases (RTKs) that cause drug tolerance in lung cancers with EGFR mutations." (PMID 34202566, 2021). "Lung adenocarcinoma (LUAD) and lung squamous cell carcinoma (LUSC) were two lung cancer subtypes, FGFR3 fusion and hotspot mutation like S249C were observed more commonly in LUSC but not in LUAD." (PMID 34160364, 2021). "Comprehensive analysis of genomic alterations in SqCC have found that mutations in FGFR2 and FGFR3 are present in ~3% of cases and account for the most frequent somatic mutations in this lung cancer subtype." (PMID 34068816, 2021). "Particularly, PRMT5-mediated increased FGFR3 signaling is caused by silencing of the miR-99 family, which negatively regulates the expression of FGFR3 in lung cancer." (PMID 34685445, 2021). "FGFR3 mutations are present at around 3% in lung cancer and the R248C mutation is known to drive tumour formation in xenograft models which were inhibited by multi-kinase inhibitor ponatinib." (PMID 24956168, 2014). "After CTTPPPD treatment, a significant reduction in FGFR3 gene expression was observed, which may help to reduce the risk of lung cancer metastasis." (PMID 39275122, 2024). "Moreover, FGFR3 was also found as one of the fusion proteins that cause acquired resistance to EGFR inhibitors in lung cancer patients." (PMID 34830951, 2021). "For other prevalent actionable mutation in lung cancer KRAS, PIK3CA, FGFR3, MET, NRAS, and RET demonstrated 100 % specificity with varied sensitivities around 50 %." (PMID 40503459, 2025). "For instance, FGFR3 fusions dominated in glioma (91.43%) and lung cancer (53.85%), while FGFR1 fusions were only observed in soft tissue sarcoma." (PMID 41092072, 2025). "According to a Japanese study, FGFR3 overexpression mediates ALK-inhibitor resistance in lung cancer." (PMID 39518064, 2024). "MiR-99 suppresses FGFR3 expression in lung cancer and Erk1/2 and Akt, reducing cell growth and metastasis." (PMID 35309302, 2022). "Inhibition of FGFR3 in a urothelial cancer cell line or FGFR1 in a lung cancer cell line resulted in decreased c-MYC protein level." (PMID 34830951, 2021). "The clinical experience in lung cancer suggests that it is feasible to evaluate the efficacy of dasatinib in combination with selective FGFR inhibitors in patients with FGFR3 molecular alterations." (PMID 32370101, 2020). "Our previous studies showed that Fibroblast growth factor receptor 3 (FGFR3) contributed to cell growth in lung cancer." (PMID 29850625, 2018). "Mutations in FGFR2 and FGFR3 have also been reported in other tumor forms, whereas activation of FGFR1 has mainly been observed in the form of FGFR1 amplification in breast and lung cancer." (PMID 29159601, 2018). "Activating mutations in FGFR1 were found in glioblastoma, FGFR2 is often mutated in endometrial carcinomas and lung cancers, FGFR3 mutations are frequently found in bladder tumors and melanoma, whereas FGFR4 is mutated in endometrial and lung cancers." (PMID 30577533, 2018). "Similar association between FGFR1, FGFR3, FGFR4 and brachyury gene expression was also observed in lung cancer cell lines." (PMID 27893433, 2016). "Although PRMT5 and p44 are ubiquitously expressed in all cancer cells, we observed heterogeneous expression of ErbB2, ErbB3, and FGFR3 in lung cancer cells and of some PRMT5/p44-target genes in various cancer cell lines in response to p44 silencing." (PMID 27480244, 2016). "BAIAP2L1(BAI1-associated protein 2-like 1) was reported as another fusion partner of FGFR3 in lung cancer patients and BC cell lines." (PMID 27930669, 2016).
lung cancer (continued). "Consistently with this conclusion, the RNA-Seq data demonstrated that lung cancer samples express high levels of ErbB2 and ErbB3 or FGFR3." (PMID 27480244, 2016). "We recently showed rapid induction of FGFR2 and FGFR3 expression in lung cancer cell lines following treatment with EGFR-specific TKIs." (PMID 25946135, 2015). "It has been reported that the overexpression of FGFR3 may promote the invasion and metastasis of lung cancer cells by activating the MAPK pathway." (PMID 39275122, 2024). "Additionally, it can target IGF-1R in gastric cancer and suppress the fibroblast growth factor receptor 3 gene in lung cancer." (PMID 36293349, 2022). "Interestingly, studies had reported that miR-99a is induced to be down-regulated when c-Src is activated, and re-overexpressed miR-99a can target mTOR/FGFR3 to inhibit Src-related oncogenic pathways and thereby inhibit the growth of lung cancer cells." (PMID 34307154, 2021). "FGFR3 fusions are more commonly observed in glioblastoma, bladder, and lung cancer." (PMID 32962091, 2020). "FGFR3 signaling is an important target for lung cancer treatment." (PMID 29545752, 2018). "FGFR3 was expressed at low levels in benign lung epithelial cells (left, indicated by red arrows) and its expression was significantly enhanced in lung hyperplasia (left, circled by red line) and in most lung cancer cells." (PMID 27480244, 2016). "However, the heterogeneity in ErbB2/3 and FGFR3 expression was observed in lung cancer cells, suggesting regulation of their expression by PRMT5/p44 may be lost in some cancer cells and their functions may be redundant in cancer cell growth." (PMID 27480244, 2016). "In lung cancer, PRMT5 downregulates miR-99 family, elevating FGFR3 and activating ERK/AKT signaling to promote tumor growth." (PMID 41204384, 2025). "We looked at the distribution of breakpoints in ALK, RET, ROS1, NTRK1, as well as other kinase genes known to generate oncogenic fusions in lung cancer, such as EGFR, ERBB4, MET, FGFR3, and EPHA245." (PMID 38877018, 2024). "In our lung cancer cohort, we also observed a 0.2% of FGFR family (mostly FGFR3) fusions and 0.02% of NTRK1/3 gene fusions." (PMID 36369474, 2022). "PRMT5 coordinates invasive phenotypes by methylating H3R2me1 for transcriptional activation and H4R3me2s for transcriptional repression, leading to FGFR3 pathway activation and TGFβ‐induced EMT in lung cancer cells." (PMID 35766227, 2022). "PRMT5 exhibits FGFR3-dependent regulation through the activation of AKT, ERK, and mTOR, and the activated FGFR signaling pathway plays an important role in promoting lung cancer cell proliferation." (PMID 36364261, 2022). "Reduced expression of miR-99 family members increases the expression of fibroblast growth factor receptor 3 (FGFR3) and, in turn, activates ERK1/2 and AKT signaling, promoting lung cancer cell migration and invasion." (PMID 34006904, 2021). "Binding was observed in two known FGFR3‐dependent cell lines, MCF7 and HepG2, in some blood‐derived cell lines and in one lung cancer‐derived cell line." (PMID 29463565, 2018). "In contrast, lung cancer samples express high levels of PRMT5, WDR77, ErbB2, ErbB3 and FGFR3 and decreased levels of GLIPR1, Leprel1 and BTG2." (PMID 27480244, 2016). "Considering the lower endogenous expression of FGFR1, FGFR3 and FGFR4 in human lung cancer cell line H441 and H358, we forced expression of full-length FGFR1, FGFR3 and FGFR4 in H441 cells." (PMID 27893433, 2016). "In human lung cancer, fibroblast growth factor 9 (FGF9), a high-affinity ligand for FGFR3, is overexpressed in 10% of primary resected non-small cell lung cancer (NSCLC) specimens." (PMID 27056048, 2016).